GDF15 (growth differentiation factor 15)
Description:
Hormone produced in response to various stresses to confer information about those stresses to the brain, and trigger an aversive response, characterized by nausea, vomiting, and/or loss of appetite. The aversive response is both required to reduce continuing exposure to those stresses at the time of exposure and to promote avoidance behavior in the future. Acts by binding to its receptor, GFRAL, activating GFRAL-expressing neurons localized in the area postrema and nucleus tractus solitarius of the brainstem. It then triggers the activation of neurons localized within the parabrachial nucleus and central amygdala, which constitutes part of the 'emergency circuit' that shapes responses to stressful conditions. The GDF15-GFRAL signal induces expression of genes involved in metabolism, such as lipid metabolism in adipose tissues. Required for avoidance behavior in response to food allergens: induced downstream of mast cell activation to promote aversion and minimize harmful effects of exposure to noxious substances (By similarity). In addition to suppress appetite, also promotes weight loss by enhancing energy expenditure in muscle: acts by increasing calcium futile cycling in muscle (By similarity). Contributes to the effect of metformin, an anti-diabetic drug, on appetite reduction and weight loss: produced in the kidney in response to metformin treatment, thereby activating the GDF15-GFRAL response, leading to reduced appetite and weight. The contribution of GDF15 to weight loss following metformin treatment is however limited and subject to discussion. Produced in response to anticancer drugs, such as camptothecin or cisplatin, promoting nausea, vomiting and contributing to malnutrition (By similarity). Overproduced in many cancers, promoting anorexia in cancer (cachexia). Responsible for the risk of nausea and vomiting during pregnancy: high levels of GDF15 during pregnancy, mostly originating from the fetus, are associated with increased nausea and vomiting. Maternal sensitivity to nausea is probably determined by pre-pregnancy exposure to GDF15, women with naturally high level of GDF15 being less susceptible to nausea than women with low levels of GDF15 before pregnancy. Promotes metabolic adaptation in response to systemic inflammation caused by bacterial and viral infections in order to promote tissue tolerance and prevent tissue damage. Required for tissue tolerance in response to myocardial infarction by acting as an inhibitor of leukocyte integring activation, thereby protecting against cardiac rupture (By similarity). Inhibits growth hormone signaling on hepatocytes (By similarity).
Synonyms: GDF-15; MIC-1; NAG-1; MIC1; PDF; PLAB; PTGFB; HG
Tractability: Antibody: UniProt places it where antibodies can reach, with high confidence; its Gene Ontology location is reachable by antibodies, with high confidence; UniProt predicts a signal peptide or a membrane-spanning region. PROTAC: ubiquitination databases record sites on it; its protein half-life has been measured.
Target class: Secreted protein
Gene: Protein-coding gene on chromosome 19 (18,374,731 to 18,389,176, forward strand). Ensembl gene ENSG00000130513.
Subcellular location: Secreted
Subcellular location (Human Protein Atlas): Golgi apparatus; Predicted to be secreted
Gene Ontology:
Molecular function: cytokine activity; hormone activity; protein binding; protein homodimerization activity; growth factor activity
Biological process: GDF15-GFRAL signaling pathway; negative regulation of appetite; negative regulation of SMAD protein signal transduction; negative regulation of transforming growth factor beta receptor signaling pathway; positive regulation of MAPK cascade; positive regulation of phosphatidylinositol 3-kinase/protein kinase B signal transduction; reduction of food intake in response to dietary excess; response to metformin; cell surface receptor protein serine/threonine kinase signaling pathway; cell-cell signaling; negative regulation of growth hormone receptor signaling pathway; negative regulation of multicellular organism growth; signal transduction; transforming growth factor beta receptor signaling pathway; cellular response to chemical stress; energy homeostasis; negative regulation of leukocyte migration; positive regulation of fatty acid oxidation
Cellular component: cytoplasm; extracellular exosome; extracellular matrix; extracellular region; Golgi apparatus; nucleus
Genetic constraint (gnomAD): Loss-of-function variants: 10 observed, 9.45 expected, observed/expected ratio (o/e) 1.06, 90% interval 0.65 to 1.72. That is too few expected variants to judge how well the gene tolerates losing a copy. Missense variants: 441 observed, 413.72 expected, observed/expected ratio (o/e) 1.07, 90% interval 0.99 to 1.15. Synonymous variants: 224 observed, 201.53 expected, observed/expected ratio (o/e) 1.11, 90% interval 1 to 1.24.
Homologues: Orthologues: chimpanzee GDF15 (97% identical), macaque GDF15 (93% identical), pig GDF15 (65% identical), dog GDF15 (63% identical), mouse Gdf15 (58% identical), guinea pig GDF15 (56% identical), rat Gdf15 (56% identical), tropical clawed frog gdf15 (25% identical). Paralogues in human: INHBE (20% identical), TGFB3 (19% identical), GDF1 (18% identical), GDF9 (18% identical), BMP15 (18% identical), GDF7 (18% identical), INHBA (18% identical), INHBB (18% identical), INHBC (18% identical), NODAL (18% identical), TGFB1 (18% identical), GDF2 (18% identical), and 19 more.
Diseases named in the same sentence as GDF15 in open-access papers:
GDF15 is named in the same sentence as 607 diseases in open-access papers, as found by Europe PMC text mining. Sharing a sentence is not in itself a finding about the gene and the disease. The quoted sentences say what the papers report.
Obesity (256 papers, 2012 to 2026). Accumulation of substantial excess body fat. "Taken together, these limitations restrict the capacity to determine causality and prevent a complete assessment of the role of GDF-15 across the triad of obesity, subclinical atherosclerosis, and HF." (PMID 41597417, 2026). "In recent years, GDF-15 has emerged as a promising biomarker, as it is involved in many of the pathological mechanisms underlying obesity, HF, and atherosclerosis." (PMID 41597417, 2026). "Based on these properties, recombinant GDF15 and GDF15 analogs have been explored as potential therapeutic agents for obesity, demonstrating robust weight loss effects in preclinical and early-phase clinical studies." (PMID 41596279, 2026). "Growth differentiation factor 15 (GDF-15) is an emerging cytokine linked to inflammation, oxidative stress, and metabolic dysregulation, which are common pathways between heart failure, obesity and atherosclerosis." (PMID 41597417, 2026). "Obesity, insulin resistance, diabetes, and fatty liver disease are positively associated with GDF-15 serum levels, reflecting metabolic and vascular stress, and endothelial dysfunction." (PMID 41597417, 2026). "Growth differentiation factor 15 is a protein involved in various bodily functions and is linked to diseases such as obesity and cancer." (PMID 41034527, 2025). "Elevated circulating GDF15 levels have been consistently associated with adverse outcomes in obesity-related metabolic disorders, heart failure, and atherosclerosis, underscoring their diagnostic and prognostic significance." (PMID 41234361, 2025). "Growth differentiation factor 15 (GDF-15) is a cytokine in the transforming growth factor β family that has attracted attention as a potential therapeutic target for obesity and its associated metabolic conditions." (PMID 39902404, 2025). "A 12-week aerobic exercise regimen performed five days per week was found to increase GDF-15 levels in individuals with obesity and was associated with fat mass reduction." (PMID 40725674, 2025). "The increase in obesity and related metabolic disorders is associated with the dysregulated production of factors like growth differentiation factor 15 (GDF15), potentially connecting metabolic stress to oncogenic pathways." (PMID 41009692, 2025). "Increased circulating GDF15 levels have been consistently associated with adverse outcomes in obesity-related metabolic disorders, heart failure, and atherosclerosis, indicating its diagnostic and prognostic significance and potential." (PMID 40837873, 2025). "This study investigated the association between plasma GDF-15 levels, diabetes mellitus, and obesity in individuals of varying ages, ethnicities, and genders." (PMID 40722664, 2025). "Further, FGF23, and GDF-15, were robustly related to PA and have been linked to metabolic disorders such as diabetes or obesity." (PMID 40498722, 2025). "Overexpression of GDF15 leads to lower energy intake and resistance to obesity, while its down-regulation is associated with increased body fat." (PMID 40837873, 2025). "Median regression indicated that elevated GDF-15 levels were independently and significantly associated with male gender, older age, obesity, diabetes, and insulin resistance." (PMID 40722664, 2025). "This study assessed changes in circulating GDF15 levels in obesity and following BS, examining their associations with anthropometric, clinical, and biochemical parameters." (PMID 40530451, 2025). "Future preclinical studies using both FGF21 and GDF15 analogues in combination should shed light on their therapeutic potential to attenuate obesity and associated comorbidities." (PMID 40897647, 2025). "On the other hand, the pluripotency of GDF15 as a marker, being considered a diagnostic/prognostic index of obesity, cancer development, and response to chemotherapy, suggests the common pathway of action/activation with other molecules." (PMID 40076962, 2025).
Obesity (continued). "GDF-15 has been shown to modulate energy balance and glucose homeostasis, and its administration leads to promising beneficial effects against obesity and associated metabolic diseases in pre-clinical models." (PMID 38791028, 2024). "Our results indicated that artesunate normalises body weight both prophylactically and therapeutically, while reversing metabolic abnormalities commonly associated with obesity in a GDF15/GFRAL axis-dependent manner." (PMID 38310105, 2024). "Members of the TGF-β superfamily such as TGF-β sensu stricto, Activins, GDF15, or Myostatins are implicated in a number of pathogeneses and metabolic diseases such as diabetes, obesity, cachexia, and cancer." (PMID 38913712, 2024). "GDF15 has been shown to reverse bulimia and obesity in obese rat models with MC4 receptor deficiency and leptin receptor deficiency." (PMID 39700016, 2024). "In recent years, GDF-15 has garnered significant interest due to its association with various chronic conditions, including cardiovascular disease, obesity, and, more recently, musculoskeletal disorders like LBP-related disability." (PMID 39595602, 2024). "This group also showed that high GDF-15 in obesity is associated with increased post-transcriptional processing of the GDF-15 precursor, pro-GDF-15, which is highly accumulated in the gastric mucosa." (PMID 39000420, 2024). "Multiple reports and recent work have repeatedly shown a decreased intake of food in animals fed a KD, indicating a potential association between GDF15 and the management of obesity by the KD." (PMID 39000187, 2024). "Progranulin is also recognized as an adipokine and, together with TNF-α and GDF-15, is known to be associated with obesity." (PMID 37371414, 2023). "GDF15 serum levels are highly elevated in association with various diseases including obesity and cancer as well as aging and have been implicated as potential biomarkers." (PMID 37373159, 2023). "Another characteristic described as being associated with elevated circulating GDF15 levels is obesity." (PMID 37891738, 2023). "GDF15 has been linked with several metabolic syndrome pathologies such as obesity and cardiovascular diseases." (PMID 36992609, 2023). "Similar results to animal tests, GDF-15 levels are correlated with obesity and also positively associated with adipose tissue mass and body weight after correcting for age and sex." (PMID 37152921, 2023). "Instead, our findings suggest that artificially sweetened drinks promote obesity and diabetes and hinder the beneficial effects of anti-diabetes medications, and this is associated with decreased circulating GDF15 levels." (PMID 37299435, 2023). "Severe outcomes have been particularly observed in patients with coexisting chronic inflammatory conditions, such as hypertension, diabetes, and obesity, which are in turn linked with elevated plasma GDF-15 levels." (PMID 35251002, 2022). "Serum GDF15 levels are elevated in both rodent models and patients with obesity and T2DM and are positively associated with body weight and AT mass." (PMID 35909571, 2022). "Similar findings that exogenous GDF15 reversed hyperphagia and obesity were also shown in leptin receptor-deficient ZF rats." (PMID 35202387, 2022). "GDF15, the only ligand detected in our study, was associated with systematic inflammation, DM and obesity." (PMID 36078120, 2022). "The serum levels of GDF15 dramatically increase in cancer-associated cachexia but are also found elevated in obesity, presumably acting as a compensatory mechanism to reduce appetite." (PMID 35454109, 2022). "We know that GDF15 potentially represents a proper indicator of disease progression since the expression of GDF15 is associated with several health problems such as obesity, diabetes, cardiovascular disease, and cancers." (PMID 35884930, 2022).
Obesity (continued). "Observed associations of GDF15 plasma levels with obesity-related diseases have been presented here and found in previous reports and variants in the GDF15 gene region have been associated with cardiovascular traits, cholesterol, WHR, and BMI." (PMID 35916366, 2022). "The negative regulation of circulating GDF15 during weight loss therapy is of particular interest, due to its regulatory role in nutritional behavior and potential implications for obesity therapy, as well as its association with NAFLD." (PMID 36430499, 2022). "Accumulating evidence has suggested that GDF-15 is a stress-responsive cytokine that is closely associated with metabolic disorders such as obesity and diabetes." (PMID 35909571, 2022). "Obesity in humans and mice is associated with elevated levels of two hormones responsive to cellular stress, namely GDF15 and FGF21." (PMID 36064109, 2022). "GDF-15 has been suggested to be a marker for those at risk for diabetes or obesity and is proposed as an emerging cardiometabolic biomarker." (PMID 34312731, 2021). "For example, obesity, the most important risk factor for EC, is also suggested to be associated with measured levels of GDF-15 and YKL-40." (PMID 33925895, 2021). "Taken together, these data support GDF15 as an intervention for obesity and its associated metabolic disorders." (PMID 33903632, 2021). "GDF15 is a potent driver of anorexia and body weight loss, and has been proposed as a therapeutic for obesity and its associated metabolic diseases." (PMID 33903632, 2021). "Due to its function, GDF15 has attracted attention as a potential therapeutic for the treatment of obesity and its associated metabolic diseases." (PMID 33903632, 2021). "The transcription factor CHOP has also been involved in obesity development and CHOP-deficient mice are more susceptible to obesity, similarly to Gdf15-deficient mice." (PMID 33302552, 2020). "Recently, it was shown that Gdf15 deletion in macrophages induces a more severe obesity and IR upon high fat diet feeding, suggesting that macrophages also participate to the obesity-associated increase of GDF-15." (PMID 33302552, 2020). "Increased GDF15 expression was significantly associated with reduced obesity and fat mass for 24 traits at 5% false discovery rate (FDR)." (PMID 32691494, 2020). "GDF15 has been suggested as a potential candidate and is associated with obesity, body weight regulation, and heart failure." (PMID 32671100, 2020). "Given the novel association between obesity severity and GDF15, we sought to evaluate the clinical implications of an elevated GDF15 to better define at risk patients." (PMID 32671100, 2020). "Plasmatic GDF-15 level increases with obesity and is positively associated with disease progression." (PMID 33302552, 2020). "GDF15 more than any other factors were higher amongst obese patients, providing an opportunity to be a salient indicator associated with obesity-related outcomes." (PMID 32671100, 2020). "This indicates that GDF15, while obesity-associated in part, can also identify significant differences with regard to outcomes over classical case histories associated with metabolic disease." (PMID 32671100, 2020). "Circulating levels of GDF-15 are associated with hyperglycaemia among people with obesity or diabetes, but longitudinal evidence on the association between GDF-15 levels and diabetes risk is scarce." (PMID 30350239, 2019). "Male sex, obesity, diabetes, and plasma levels of cystatin C, GDF‐15, and CRP‐hs were independently associated with higher IL‐18 levels." (PMID 31596518, 2019). "GDF15 knockout mice were more obese, making it difficult to dissect if GDF15 deficiency caused higher skin lesion incidences through primary effect or indirectly by promoting obesity." (PMID 30070999, 2018). "Previous studies convincingly demonstrated that GDF15 shapes the susceptibility to developing obesity and that GDF15 treatment ameliorated diet-induced obesity." (PMID 30533221, 2018).